STX12 (syntaxin 12)
Description:
SNARE promoting fusion of transport vesicles with target membranes. Together with SNARE STX6, promotes movement of vesicles from endosomes to the cell membrane, and may therefore function in the endocytic recycling pathway. Through complex formation with GRIP1, GRIA2 and NSG1 controls the intracellular fate of AMPAR and the endosomal sorting of the GRIA2 subunit toward recycling and membrane targeting.
Synonyms: STX13; STX14
Tractability: Antibody: UniProt places it where antibodies can reach, with medium confidence; UniProt predicts a signal peptide or a membrane-spanning region. PROTAC: ubiquitination databases record sites on it; its protein half-life has been measured.
Gene: Protein-coding gene on chromosome 1 (27,773,195 to 27,824,443, forward strand). Ensembl gene ENSG00000117758.
Subcellular location: Endosome membrane; Golgi apparatus membrane; Endomembrane system; Early endosome membrane; Recycling endosome membrane
Subcellular location (Human Protein Atlas): Golgi apparatus; Nucleoplasm; Vesicles
Gene Ontology:
Molecular function: protein binding; SNARE binding; SNAP receptor activity
Biological process: autophagosome assembly; cholesterol efflux; protein stabilization; endocytic recycling; intracellular protein transport; membrane fusion; vesicle-mediated transport
Cellular component: BLOC-1 complex; Golgi apparatus; membrane raft; phagocytic vesicle; phagophore assembly site; SNARE complex; vesicle; early endosome membrane; endomembrane system; endosome membrane; Golgi membrane; postsynaptic recycling endosome; recycling endosome; recycling endosome membrane; synaptic vesicle; synaptic vesicle membrane; cytoplasmic vesicle; membrane
Genetic constraint (gnomAD): Loss-of-function variants: 9 observed, 27.58 expected, observed/expected ratio (o/e) 0.33, 90% interval 0.2 to 0.57. The upper end of that interval is the gene's LOEUF score, 0.57, which puts it in group 2 of 6, group 1 being the genes least tolerant of losing a copy. Missense variants: 241 observed, 262.41 expected, observed/expected ratio (o/e) 0.92, 90% interval 0.83 to 1.02. Synonymous variants: 84 observed, 95.62 expected, observed/expected ratio (o/e) 0.88, 90% interval 0.74 to 1.05.
Homologues: Orthologues: chimpanzee STX12 (100% identical), guinea pig STX12 (95% identical), dog STX12 (95% identical), pig STX12 (94% identical), mouse Stx12 (92% identical), rat Stx12 (85% identical), zebrafish stx12 (67% identical), tropical clawed frog stx12 (66% identical), zebrafish stx12l (64% identical), Drosophila melanogaster Syx7 (33% identical), Caenorhabditis elegans syx-7 (33% identical). Paralogues in human: STX7 (51% identical), TSNARE1 (29% identical), STX16 (25% identical), STX1B (25% identical), STX1A (24% identical), STX2 (24% identical), STX3 (24% identical), STX4 (22% identical), STX5 (21% identical), STX17 (19% identical), STX11 (18% identical), STX19 (18% identical).
Diseases named in the same sentence as STX12 in open-access papers:
STX12 is named in the same sentence as 22 diseases in open-access papers, as found by Europe PMC text mining. Sharing a sentence is not in itself a finding about the gene and the disease. The quoted sentences say what the papers report.
gastric cancer (2 papers, 2022 to 2025). A primary or metastatic malignant neoplasm involving the stomach. "Our subsequent studies will further explore the role and value of STX12 in gastric cancer." (PMID 39858034, 2025). "So far, there has been no report on the roles of STX12 in gastric cancer, which may necessitate further studies." (PMID 36400805, 2022).
hepatoma (2 papers, 2020 to 2022). "The positive association between NFE2L1 and STX12 expression was validated by immunohistochemistry of the hepatocellular carcinoma tissue array." (PMID 32942643, 2020). "STX12 was upregulated through the ROS/STAT3/NFE2L1 axis in hepatoma cells, and it was a key downstream effector of NFE2L1 in modulating hepatoma cell invasiveness." (PMID 36400805, 2022). "The present study demonstrates that NFE2L1 is one of the reprogrammed gene products critically involved in hepatoma cell invasiveness via the expression of STX12." (PMID 32942643, 2020). "Collectively, our results indicate that NFE2L1 is a key mitochondrial retrograde signaling-mediated primary gene product enhancing hepatoma cell invasiveness via STX12 expression and promoting liver cancer progression." (PMID 32942643, 2020). "Collectively, our results indicate that NFE2L1 is a key mitochondrial retrograde signaling-mediated gene product enhancing hepatoma cell invasiveness via STX12 expression." (PMID 32942643, 2020). "In this study, we presented STX12 as a key downstream driver of NFE2L1 to induce hepatoma cell invasiveness." (PMID 32942643, 2020). "The knockdown of STX12 in SNU423 cells suppressed cell invasiveness, whereas the overexpression of STX12 in Ch-L cells induced invasiveness, implying that STX12 is an essential and sufficient regulator of hepatoma cell invasiveness." (PMID 32942643, 2020). "In this study, we demonstrate that the mitochondrial OXPHOS defect enhances NFE2L1 transcription via reactive oxygen species (ROS)-mediated STAT3 activation, and the upregulation of NFE2L1 increased hepatoma cell invasiveness by inducing syntaxin 12 (STX12) expression." (PMID 32942643, 2020). "Taken together, these results indicate that NFE2L1/STX12 expression is the key to regulating hepatoma cell invasiveness and may be useful as a prognostic marker for HCC." (PMID 32942643, 2020). "NFE2L1 is the key transcription factor to enhance hepatoma cell invasiveness via STX12 expression." (PMID 32942643, 2020). "Next, we investigated the role of STX12 in hepatoma cell invasiveness." (PMID 32942643, 2020). "We further demonstrated that STX12 is upregulated through the ROS/STAT3/NFE2L1 axis and is a key downstream effector of NFE2L1 in modulating hepatoma cell invasiveness." (PMID 32942643, 2020). "We identified syntaxin 12 (STX12) as an effective downstream target of NFE2L1 by performing cDNA microarray analysis after the overexpression and depletion of NFE2L1 in hepatoma cells." (PMID 32942643, 2020).
liver cancer (2 papers, 2020 to 2024). An epithelial or non-epithelial malignant neoplasm that arises from the liver. "Next, to validate the relationship between NFE2L1 and STX12 protein expression, we performed immunohistochemistry using a liver cancer tissue array." (PMID 32942643, 2020). "Our study presents a novel mitochondrial dysfunction-mediated retrograde signaling pathway and the resulting transcriptomic reprogramming in liver cancer progression, providing the NDUFA9/NFE2L1/STX12 axis as a key prognostic marker of aggressive liver cancer with mitochondrial defects." (PMID 32942643, 2020).
cardiac hypertrophy (1 paper, 2025). "Conditional Stx12 knockout in the heart results in cardiac hypertrophy and heart failure with cardiac mitochondrial morphological changes and energy deficiency." (PMID 40568929, 2025). "Taken together, the presence of pericardial edema in Stx12‐deficient zebrafish, cardiac malformation in Stx12‐KO mice, and cardiac hypertrophy in conditional Stx12 knockout mice consistently suggested that STX12 was crucial for maintaining normal cardiac function." (PMID 40568929, 2025). "Mice with conditional Stx12 knockout in the heart were not lethal but displayed signs of cardiac hypertrophy within three months." (PMID 40568929, 2025).
cardiomyopathies (1 paper, 2025). "Enhancing mitochondrial function, autophagy, and SERCA activity through the administration of rapamycin may provide a potential therapeutic approach for cardiomyopathies associated with STX12 deficiency and hypometabolism." (PMID 40568929, 2025). "Since STX12 deficiency causes the decreased activity of SERCA2a, enhancing SERCA2a activity could be a viable therapeutic strategy for STX12‐related cardiomyopathies." (PMID 40568929, 2025).
heart failure (1 paper, 2025). Inability of the heart to pump blood at an adequate rate to meet tissue metabolic requirements. "Rapamycin intervention effectively alleviates heart failure symptoms caused by STX12 deficiency through mechanisms involving augmented autophagy, rejuvenation of mitochondrial function, and restoration of SERCA activity." (PMID 40568929, 2025). "Stx12 deficiency causes heart failure via impaired iron trafficking to mitochondria, reducing respiratory complexes and sarcoplasmic reticulum Ca2+‐ATPase (SERCA)." (PMID 40568929, 2025). "Collectively, these findings substantiated that cardiac STX12 deficiency caused heart failure in mice." (PMID 40568929, 2025). "Using zebrafish and mice, it is shown that STX12 loss leads to pericardial edema, cardiac malformations, and heart failure." (PMID 40568929, 2025). "Considering that rapamycin could effectively ameliorate malfunctions of cardiomyocytes caused by STX12 deficiency in vitro, we aimed to investigate the effectivity of rapamycin on alleviating heart failure in vivo." (PMID 40568929, 2025). "In contrast, Stx12‐cKO mice had an EF% value of 47.4 ± 7.5% (t‐test, p = 0.0006), and an FS% value of 23.4 ± 4.2% (t‐test, p = 0.0004) (data in mean ± SD), indicating the occurrence of heart failure." (PMID 40568929, 2025). "Taken together, rapamycin treatment could enhance both mitochondrial protein biosynthesis and SERCA2a activation, ultimately contributing to the amelioration of heart failure in Stx12‐cKO mice." (PMID 40568929, 2025). "Therefore, the cardiac Stx12‐cKO mouse is a valuable model for intervening in hypometabolism of heart failure." (PMID 40568929, 2025). "We found an upregulation of MYH7 in Stx12‐cKO mice, providing extra evidence of heart failure." (PMID 40568929, 2025). "Rapamycin alleviates heart failure via TFEB and CaMKII pathways in Syntaxin 12/13 deficient models." (PMID 40568929, 2025). "In summary, our findings have demonstrated that STX12 deficiency may hinder iron transportation to mitochondria, impairing mitochondrial morphology and function, causing hypometabolism and metabolic reprogramming, decreasing the activity of SERCA, and eventually resulting in heart failure." (PMID 40568929, 2025).
prostate carcinoma (1 paper, 2015). A carcinoma that arises from epithelial cells of the prostate gland. "There was a trend for lower expression of ALIX (PDCD6IP) to stratify patients with increased prostate cancer recurrence (P = 0.059), and reduced expression of Syntaxin 12 (STX12) was also indicative of at-risk patients, with significant stratification (P = 0.001)." (PMID 26473288, 2015). "In the current study, quantitation of gene signatures for the early endosomal genes APPL1, EEA1 and RAB5A, and analysis of the endosomal genes MYO1B, PDCD6IP and STX12 in prostate cancer patients expressing PSA ≤ 10 ng/mL, led to patient stratification into high and low-risk recurrence groups." (PMID 26473288, 2015).
schizophrenia (1 paper, 2012). A major psychotic disorder characterized by abnormalities in the perception or expression of reality. "Therefore, downregulation of STX12 in the STG of schizophrenia patients implies a subtle impairment of synaptogenesis." (PMID 22441714, 2012).
viral infection (1 paper, 2025). "Some of the upregulated proteins, including SPRK1, STX12, and UQCRH, have been reported to be relevant to viral infection and replication." (PMID 40920846, 2025).
cancer (6 papers, 2016 to 2025). A tumor composed of atypical neoplastic, often pleomorphic cells that invade other tissues. "From this analysis, 10 commonly regulated genes were identified, and we validated the role of four genes (ENO2, EphB2, SerpinE1, and STX12), which were reportedly involved in cancer cell activities, as downstream targets of NFE2L1." (PMID 32942643, 2020). "Our findings reveal that miR-142-3p overexpression not only reduces ULK1 protein levels but downregulates lysosomal function-associated gene SLC17A5, and the autophagosome–lysosome attachment gene STX12, highlighting its potential to disrupt autophagy and lysosomal processes in cancer cells." (PMID 40362400, 2025). "Indeed, knockdown of PRDX6, PLCβ4 or STX12 in five additional cancer cell lines similarly affected DTP formation." (PMID 27484502, 2016). "In addition to these, we found many other proteins like STX12, TATA-binding protein L1, and TOP 2B, which have a variable role in cancer." (PMID 38961106, 2024). "DEF8, NDUFC2, GUSBP1, ARIH2, STX12 and HIST1H2BN were highly re-expressed (more than 100 folds) in either treatment of MV4-11, have not been previously discussed on their role in cancer except for HIST1H2BN." (PMID 32337016, 2020).
tumour (4 papers, 2009 to 2024). "In contrast to the upregulated DEGs, we discovered that STX12 expression was significantly and consistently lower in tumor compared to normal tissues in all three GC cohorts." (PMID 36400805, 2022). "Similarly, STX12 expression was significantly reduced while the expression of the other eight genes increased in tumor tissues (P < 0.05 in two-tailed t test)." (PMID 36400805, 2022).
infection (2 papers, 2023 to 2025). The state of being infected such as from the introduction of a foreign agent such as serum, vaccine, antigenic substance or organism. "Serine/arginine-rich splicing factor protein kinase-1 (SRPK1), syntaxin 12 (STX12) and ubiquinol-cytochrome c reductase hinge protein (UQCRH) from the upregulated group have been reported to be related to the infection and replication of certain kinds of viruses." (PMID 40920846, 2025). "Interestingly, the strongest decrease in infection was detected for the knockouts of three vesicular trafficking proteins (VTI1A, STX12 and STX16), highlighting the important role of vesicular trafficking for SARS-CoV-2 infection and replication." (PMID 37632105, 2023).
STX12 also shares sentences with these, for which no sentence is quoted: bladder cancer (1 paper); breast carcinoma (1); colon cancer (1); diabetes (1); fibrosarcoma (1); lung adenocarcinoma (1); lung carcinoma (1); metabolic disorders (1); neuroblastoma (1); Ventricular hypertrophy (1).